GUSB (glucuronidase beta)
Diseases named in the same sentence as GUSB in open-access papers (continued):
Sharing a sentence is not in itself a finding about the gene and the disease.
head and neck squamous cell carcinoma (1 paper, 2025). A squamous cell carcinoma that arises from any of the following anatomic sites: lip and oral cavity, nasal cavity, paranasal sinuses, pharynx, larynx, and salivary glands. "A recent study found that the allosteric mutation H351Q in the β-glucuronidase (GUSB) gene can significantly promote tumor progression in head and neck squamous cell carcinoma (HNSCC)." (PMID 40963867, 2025).
Hernia (1 paper, 2006). "All twelve exons of the porcine GUSB gene were screened for SNPs to evaluate a possible contribution of the gene in the inheritance of hernia." (PMID 16646965, 2006).
Hyperglycemia (1 paper, 2014). An increased concentration of glucose in the blood. "Under hyperglycemia combined with hypoxia, gene expression of GUSB, TFRC, RPLP0, and ACTB turned out to be stable in all time intervals measured (1, 3, and 12 hr)." (PMID 25193495, 2014). "Under hyperglycemia combined with hypoxia up to 12 hr, the expression of RPLP0, TFRC, GUSB, and ACTB genes remained unchanged." (PMID 25193495, 2014).
Hyperinsulinemia (1 paper, 2021). An increased concentration of insulin in the blood. "Hyperinsulinemia, however, did not change GUSB, slightly decreased CTSL expression and increased TFRC levels, all of these changes being significantly different from the metformin effects." (PMID 33690729, 2021).
Inguinal hernia (1 paper, 2006). Protrusion of the contents of the abdominal cavity through the inguinal canal. "On the basis of our studies we are able to exclude the two analyzed SNPs within the porcine GUSB gene as causative for the transmission of inguinal hernia." (PMID 16646965, 2006).
Intellectual disability (1 paper, 2022). "Another 7-year-old male with intellectual disability, corneal clouding was identified to have a homozygous VUS in GUSB gene causative of MPS VII." (PMID 35123515, 2022).
Kanzaki disease (1 paper, 2021). "Mutations in GUSB, CLN6, and PPT1 cause Sly disease, neuronal ceroid lipofuscinosis (CLN6), and neuronal ceroid lipofuscinosis (CLN1), respectively, whereas mutations in GALNS and NAGA cause Morquio A disease and Schindler disease/Kanzaki disease, respectively." (PMID 34867278, 2021).
lymph node metastasis (1 paper, 2022). "The subgroup study according to stages, tumor grade, and lymph node metastasis showed that the higher cancer stage, grades, and lymph node metastasis, the higher GUSB expression." (PMID 35812439, 2022).
melanoma (1 paper, 2016). A malignant, usually aggressive tumor composed of atypical, neoplastic melanocytes. "In addition, we identify five genes (ALG12, GUSB, RPLP0, KRBA2, and ADAT2) that are stably expressed in melanoma cells independent of the presence of T cells or the T cell-derived cytokines IFNγ and TNFα." (PMID 27625650, 2016).
metastatic disease (1 paper, 2023). "CDC6, DHFR, E2F1, H2AFZ, MCM2, GUSB and B2M were significantly higher in patients with metastatic disease than in healthy controls, and CDC6, DHFR and E2F1 were significantly higher in metastatic patients than in localized patients." (PMID 37046768, 2023).
mucolipidosis type II (1 paper, 2025). Mucolipidosis II (MLII) is a slowly progressive lysosomal disorder characterized by growth retardation, skeletal abnormalities, facial dysmorphism, stiff skin, developmental delay and cardiomegaly. "Indeed, triclabendazole reduced the transduced GAG core proteins in the MPS model cells, including IDUA KO cells, ARSB KO cells, and GUSB KO cells, as well as in GNPTAB KO cells, a model cell for mucolipidosis type II." (PMID 40822349, 2025).
mucopolysaccharidosis VI (1 paper, 2025). "Two patients carrying known pathogenetic GALC variants were also heterozygous for other known pathogenetic variants in other LSD‐associated genes, including HEXB (Sandhoff disease) and GUSB (mucopolysaccharidosis VI)." (PMID 40391866, 2025).
multinodular goiter (1 paper, 2019). Nodular goiter characterized by more than one discrete tissue mass. "The expression characteristics of 12 candidate reference genes (GAPDH, ACTB, HPRT1, TBP, B2M, PPIA, 18SrRNA, HMBS, GUSB, PGK1, RPLP0, and PGM1) were assessed by qRT-PCR in 45 thyroid tissue samples (15 papillary thyroid carcinoma, 15 paired normal tissues and 15 multinodular goiters)." (PMID 31645594, 2019).
nasal polyps (1 paper, 2018). "GUSB and ATPase plasma membrane Ca2+ transporting 4 (ATP2B4) were identified as reliable genes for normalization of cystic fibrosis transmembrane conductance regulator (CFTR) gene expression in the nasal mucosa and nasal polyps in patients with cystic fibrosis." (PMID 29371606, 2018).
ovarian carcinoma (1 paper, 2017). A malignant neoplasm originating from the surface ovarian epithelium. "Recently, it is reported that B2M and 18S RNA are suitable internal reference genes in serum stimulated samples; GUSB and PPIA are believed to serve as internal reference genes in ovarian cancer, while RPL13A is identified to stably transcript in ovarian cancer cells treated with PTX and HCPT." (PMID 28184026, 2017).
prostate carcinoma (1 paper, 2019). A carcinoma that arises from epithelial cells of the prostate gland. "(b) Distribution of transcript levels of splicing regulators DDX5, DDX17 and QKI, assessed by RT-qPCR and normalized to GUSB, in androgen positive and negative prostate cancer cell lines." (PMID 31164793, 2019).
steatosis (1 paper, 2025). Increased lipid within the cytoplasm of cells. "Of 12 proteins in the SomaSignal test for steatosis, two (PTGR1 and GUSB) showed a statistically significant lower abundance for semaglutide 0.4 mg versus placebo." (PMID 40691365, 2025).
uveal melanoma (1 paper, 2025). A melanoma derived from melanocytes of the uveal tract. "In the uveal melanoma cohort, a six‐molecule signature (ARPC1B, BTBD6, GUSB, KRTCAP2, RHBDD3, and SLC39A4), which was associated with glycolysis and the immune response, was established and used for survival prediction and risk stratification of these patients." (PMID 39830021, 2025).
tumor (26 papers, 2007 to 2025). "In this study, we integrated WES and AlloDriver to identify allosteric driver mutations in HNSCC and found that the specific mutation H351Q in β‐glucuronidase (GUSB) was a potential novel molecular mechanism for tumor progression." (PMID 39830021, 2025). "As a member of the GRG signature, GUSB was reported for the first time to be positively associated with poor tumor prognosis." (PMID 39830021, 2025). "GUSB inhibition can significantly improve human cancer therapy with irinotecan and various glucuronidating chemotherapeutic drugs that cause intestinal toxicity and reduce tumor size." (PMID 35812439, 2022). "GUSB has been less frequently reported to participate in the immune response, especially in the tumor microenvironment." (PMID 39830021, 2025). "In vivo GUSB activity can be transformed into urinary signals, which serve as biomarkers for the quantitative monitoring of tumor progression." (PMID 39830021, 2025). "The tumor growth of the GUSB‐H351Q cells was identical to that of the BALB/c nude mice, further confirming the protumoral efficacy of this pivotal mutation." (PMID 39830021, 2025). "Next, we investigated the metabolic alterations between the GUSB‐WT and H351Q tumor microenvironments." (PMID 39830021, 2025). "In contrast, patients with insufficient expression of SORBS2, PAM, ZFAT, DOCK7, ERMAP, BTF3, and GUSB in the tumor tissues had shorter survival duration than patients in the high-expression group." (PMID 37315301, 2023). "As indicated from the result, the expression level of CD45+ immune cells was remarkably increased in the sh-GUSB part compared to the sh-NC part, suggesting that the reduction of GUSB would massively activate tumor immune infiltration." (PMID 35812439, 2022). "HMGA2/GUSB values ranged between 1 and 26.8 in the control samples, 44.4 and 2330 in the tumour samples, and 319 and 1092 within the cell culture samples." (PMID 25245141, 2014). "HMGA1/GUSB expression levels varied from 0.225 to 1.47 within the control samples, and from 0.53 to 2.52 within the tumour samples." (PMID 25245141, 2014). "HMGA1 was up-regulated when GUSB was used as endogenous control gene within the tumour samples (p = 0.0011) when compared to the non neoplastic samples." (PMID 25245141, 2014). "First, PlGF mRNA expression, normalized for expression of the housekeeping gene GUSB, was quantified in tumor tissues and compared to the expression levels in normal endometrial tissue." (PMID 23232836, 2013). "Amongst seven commonly used classical housekeeping genes, we found that expression levels of ACTB, GAPDH, GUSB and 18S rRNA, significantly differed between tumor and normal tissues on the basis of the examination of raw CT values." (PMID 19257903, 2009). "ACTB, GAPDH and GUSB mRNA levels are significantly increased in tumor samples, with changes of about 3.6, 3.5 and 4.7 fold, respectively; while 18S rRNA was revealed to be slightly diminished in tumor samples, in a proportion of approximately 13%." (PMID 19257903, 2009). "The ΔCt between CDKN1C and GUSB for each normal sample was compared to its paired tumor sample to generate the relative expression of CDKN1C mRNA between tumor and normal." (PMID 18325103, 2008). "Allosteric mutation of GUSB may be a novel modulator of aberrant PD‐L1 N‐glycosylation in HNSCC, which provides potential methods to inhibit tumor growth and increase immunotherapy efficacy." (PMID 39830021, 2025).
tumor (continued). "This mutation causes GUSB protein to be retained in the endoplasmic reticulum, enhancing the stability and transcription of the STT3B subunit, thereby promoting aberrant N-glycosylation of PD-L1, which contributes to tumor immune evasion." (PMID 40963867, 2025). "Additionally, the UALCAN database revealed that GUSB expression in tumor tissues was clearly higher than that in normal tissues." (PMID 35812439, 2022). "Notably, we studied the immune invasion of Hepa1-6 tumors (sh-NC, sh-GUSB) in mice 20 days after tumor injection by mass spectrometry." (PMID 35812439, 2022). "Previous literature has reported that the older drug amoxapine could act as an effective GUSB inhibitor to reduce tumor growth." (PMID 35812439, 2022). "ACTB and GUSB selection, based on geNorm analysis including the seven potential housekeeping genes, probably resulted from similarities in the expression pattern of these two genes, which are both significantly up regulated in tumor tissues, as well as GAPDH." (PMID 19257903, 2009). "Likewise, future studies are needed in a tumor xenograft model to test whether the reduced n-6/n-3 ratio maintains the efficacy of CPT-11 while reducing the GUSB activity." (PMID 35628140, 2022). "GUSB expression has been correlated with increased invasion of tumor cells, however, it remains unclear, whether an increased expression of GUSB is directly involved in tumor progression or is just upregulated during the process and rather serves as a marker for invasiveness." (PMID 33690729, 2021). "However, there are no data concerning whether the GUSB transcript or mutations play a defined role in tumor progression and the underlying mechanism." (PMID 39830021, 2025). "In our study, the expression stability of five reference genes ACTB, ALAS1, GUSB, HMBS, and RPL29 were investigated to determine the CRM1 gene expression profile in tumor tissues and normal tissues by NormFinder analysis." (PMID 38031942, 2023). "We tested 24 tumor samples for BRCA1 and BRCA2 mRNA levels, normalized to the reference genes GUSB, POLR1E, and NUBP1." (PMID 35203410, 2022). "Relative GUSB and SDHA expression was up-regulated in SW620 (line derived from secondary tumor), significantly in case of GUSB." (PMID 27339468, 2016). "HMGA2 was up-regulated when GUSB and HPRT were used as endogenous control genes within the tumour samples when compared to the non neoplastic controls." (PMID 25245141, 2014). "HMGA2 was up-regulated when GUSB and HPRT were used as endogenous control genes within the tumour and cell line samples when compared to the non neoplastic samples." (PMID 25245141, 2014). "The respective p-values of the tumour and cell line sample groups were p = 0.000 despite of the cell line sample group within the HMGA2/GUSB real time PCR showing a p-value of 0.001." (PMID 25245141, 2014). "Therefore, knockdown of GUSB in cancer cells can 1) inhibit the growth of cancer cells, 2) increase NK and CD8+ T cells in the tumor microenvironment and decrease immunosuppressive cells such as Tregs and M2 macrophages." (PMID 35812439, 2022). "The results of our analysis proved that the expression of reference genes in our cohort of patients, including only endometrioid histotype and carefully selected and balanced according to their tumor grade, was dependent on tumor grade for B2M, GAPDH, H3F3A, GUSB, HPRT1, POLR2A and UBC." (PMID 25473950, 2014). "Genes, whose expression levels did not significantly vary between tumor and normal tissues, would be considered significantly diminished when normalized with GUSB or increased when normalized with 18S rRNA." (PMID 19257903, 2009). "Moreover, GUSB‐H351Q reshaped a more immunosuppressive microenvironment featuring increased infiltration of exhausted CD8+ T cells and remodeled tumor metabolism, characterized by increased activity of the purine metabolism pathways and pyruvic acid accumulation." (PMID 39830021, 2025).
tumor (continued). "On day 20, the tumor volume and weight of the sh-GUSB group were significantly smaller than those of the sh-NC group, and the tumor volume and weight of the sh-GUSB +anti-PD1 group were significantly smaller than those of the sh-GUSB group and sh-NC +anti-PD1 group." (PMID 35812439, 2022). "Among seven genes whose expression levels did not significantly vary between tumor and normal tissues, five (71%) would be considered significantly diminished when normalized with GUSB and six (86%) would be considered significantly increased when normalized with 18S rRNA." (PMID 19257903, 2009). "Therefore, we can conclude that for GBM gene expression studies, GUSB along with the most frequently utilized internal controls, ACTB and GAPDH, must be considered inadequate for normalizations due to its significant increase in tumor samples." (PMID 19257903, 2009). "Amplification of EPOR in amplicons <10 Mb was identified in less than 0.7% of tumours (n=8) and was similar to the frequency of amplification of other established non-oncogenic loci such as glyceraldehyde-3-phosphate dehydrogenase (GAPDH), β-actin (ACTB), and β-glucuronidase (GUSB)." (PMID 18349818, 2008). "The tumor samples were negative for GUSB activity and the rAAV genome could not be detected in the tumor genome by polymerase chain reaction (PCR) using primers specific for the transgene GUSB cDNA, thus suggesting that the tumors were probably not caused by insertional mutagenesis." (PMID 35690906, 2022). "GUSB was the most stable RG in group I (all samples), GAPDH in group II (paired 70 T + 70 C), followed by RPL13 in groups III (35 nonmetastatic vs 35 mccRCC) and IV (matched tumor-metastasized control group of samples)." (PMID 25225161, 2014).
cancer (20 papers, 2008 to 2025). A tumor composed of atypical neoplastic, often pleomorphic cells that invade other tissues. "MPS Type VII (Sly syndrome) caused by β−glucuronidase deficiency involving the GUSB gene, has also been linked to cancer development." (PMID 37601653, 2023). "GUSB‐H351Q was identified as a previously unrecognized mediator of aberrant PD‐L1 glycosylation characterized by increased expression of complex branched N‐glycans, which are associated with immune evasion and cancer progression." (PMID 39830021, 2025). "Using quantitative PCR, we quantified IKKε (IKBKE) and TBK1 mRNA via normalization to a GUSB internal control in different KRAS mutant cancer cells." (PMID 40738190, 2025). "Increased cancer prevalence has also been reported in carriers of a potentially pathogenic variant of an LSD gene, namely CLN3, SGSH, GUSB, NEU1, and, to a lesser extent, in other genes." (PMID 39404425, 2024). "It was found that increased GUSB expression in HCC cells promotes cancer cell growth, reduced PD-L1 expression, and immunosuppression." (PMID 37601653, 2023). "The knockdown of GUSB enhanced the anti-HCC effect when combined with anti-PD1 therapy in vivo, which adds luster to the new function of GUSB in cancer." (PMID 35812439, 2022). "We found reduced expression of CDKN1C in 9/10 (90%) cancers relative to its paired normal epithelium, and normalized against GUSB." (PMID 18325103, 2008). "Through validation of the function of the allosteric site H351Q of GUSB in vitro and in vivo, we report, for the first time, the novel function of the normalization gene GUSB as a pivotal driver mutation in cancer development." (PMID 39830021, 2025). "First, fecal GUSB activity and tissue n-6/n-3 ratio could be utilized as biomarkers to micro-type patients with cancer receiving Irinotecan and improving its pharmacokinetics or reducing its toxicity." (PMID 35628140, 2022). "However, the functional mutation of GUSB in cancer, especially allosteric sites, has not been elucidated." (PMID 39830021, 2025). "The quantitative analysis of the gene expression involves five reference genes (ACTB, TFRC, GAPDH, GUSB, and RPLP0) and 16 cancer-related genes." (PMID 36042999, 2022). "As before, we compared the expression of PKC coding genes in normal and cancer tissue with the data normalised to either PGK1 alone or PGK1, GUSB and PP1A together." (PMID 26962435, 2016). "Using normal and cancer tissue from CRC patients we examined the stability of the nine candidate reference genes, finding PGK1, GUSB and PP1A to be the most stably expressed." (PMID 26962435, 2016). "To date, the role of GUSB in malignant tumors has not been clearly defined." (PMID 39830021, 2025). "However, there are not many studies on GUSB directly against cancer." (PMID 35812439, 2022). "A small number of hypoxia-associated genes (APLN, HIF1A, and BNIP3), cancer stem cell (CSC) markers (CD24 and CD44), hormonal regulation (HR) genes (ESR1, PGR, and TFF1), other selected genes (PPARGC1A, ILK), and HKGs (RPL32, GUSB, TBP, OAZ1 and NONO) were also included in the panel." (PMID 34206049, 2021). "For the Test Cancer BioChip, the negative controls employed included non-targeting, ACTB, GUSB, GAPDH, RPLP0, TFRC and cyclophilin siRNA as well as no siRNA." (PMID 23049944, 2012). "Interestingly, we observed that GAPDH, GUSB, IPO8, RPL13, RPL32, and UBC genes, as well as RPLP0 + TBP, RPL13 + RPL32, RPL13 + RPLP0, and ACTB + TBP RG pairs, were the only assays whose expression did not depend (P > 0.05) on cancer progression." (PMID 25225161, 2014).
infection (4 papers, 2011 to 2023). The state of being infected such as from the introduction of a foreign agent such as serum, vaccine, antigenic substance or organism. "In this purview, the presence of infection-associated proteins (GUSB, GZMB, LEAP2, LY6D) in estrus urine is interesting." (PMID 37104448, 2023). "In contrast, beta-2-microglobulin (B2M) was slightly upregulated in MP12 and ZH548 infected cells at 18 hpi and glucuronidase beta (GUSB) was not altered after infection." (PMID 29085037, 2017). "The reference genes B2M and/or GUSB were selected since their expression did not change significantly following infection." (PMID 27978534, 2016).
skeletal disease (1 paper, 2012). "In summary, we describe a severe canine skeletal disease and identify a syndrome-defining mutation in the GUSB gene." (PMID 22815736, 2012).